URGCP-MRPS24 (URGCP-MRPS24 readthrough)
Gene: Protein-coding gene on chromosome 7 (43,866,558 to 43,906,589, reverse strand). Ensembl gene ENSG00000270617.
Genetic constraint (gnomAD): Loss-of-function variants: 11 observed, 19.62 expected, observed/expected ratio (o/e) 0.56, 90% interval 0.35 to 0.93. The upper end of that interval is the gene's LOEUF score, 0.93, which puts it in group 3 of 6, group 1 being the genes least tolerant of losing a copy. Missense variants: 127 observed, 150.98 expected, observed/expected ratio (o/e) 0.84, 90% interval 0.73 to 0.98. Synonymous variants: 49 observed, 55.59 expected, observed/expected ratio (o/e) 0.88, 90% interval 0.7 to 1.12.